SNORD19C (small nucleolar RNA, C/D box 19C)
Gene: Small nucleolar RNA gene on chromosome 3 (52,691,378 to 52,691,453, forward strand). Ensembl gene ENSG00000222345.
Gene Ontology:
Biological process: RNA processing
Cellular component: nucleolus
Homologues: Orthologues: rabbit SNORD19C (92% identical). Paralogues in human: SNORD19 (57% identical).